GFAP (glial fibrillary acidic protein)
Diseases named in the same sentence as GFAP in open-access papers (continued):
Sharing a sentence is not in itself a finding about the gene and the disease.
amyotrophic lateral sclerosis (33 papers, 2011 to 2025). Amyotrophic lateral sclerosis (ALS) is a neurodegenerative disease characterized by progressive muscular paralysis reflecting degeneration of motor neurons in the primary motor cortex, corticospinal tracts, brainstem and spinal cord. "While GFAP fragmentation plays a physiological role in astrocyte remodelling, its dysregulation has been linked to neurodegenerative diseases such as AD, amyotrophic lateral sclerosis, and TBI." (PMID 40690136, 2025). "In amyotrophic lateral sclerosis patients, differential GFAP acetylation was observed at K89, K153, K189, K218, K259, and K331 sites of GFAP in the spinal cord." (PMID 40690136, 2025). "GFAP expression is increased in several disorders and injuries of the central nervous system including AD 35,36, amyotrophic lateral sclerosis 37, and multiple system atrophy 38, as well as rodent models of traumatic brain injury 39,40." (PMID 31754385, 2019). "Increase in calpain-generated GFAP fragments was similarly detected in the spinal cord of amyotrophic lateral sclerosis and in experimental brain injury of rodents as well as in cerebrospinal fluid (CSF) of traumatic brain injury patients." (PMID 28700643, 2017). "Neuronal expression of GFAP has been reported by chromatin marks in healthy young adult mouse brains, human AD by IHC and single nucleus RNAseq, in motor neurons in a mouse model of amyotrophic lateral sclerosis, and in synaptasomes of human PrD." (PMID 35960762, 2022). "In the SOD1 transgenic mouse model of Amyotrophic Lateral Sclerosis (ALS), reactive and hypertrophic astrocytes upregulate GFAP expression in the spinal cord." (PMID 35535566, 2022). "As an example, Keller and coworkers investigated the expression of glial fibrillary acidic protein (GFAP) during the progression of amyotrophic lateral sclerosis (ALS)." (PMID 22346573, 2011). "In previous work, we addressed the role of astrocytic IKK2/NF-κB activation in amyotrophic lateral sclerosis (ALS) pathogenesis using the tetracycline-regulated expression of constitutively active IKK2 (IKK2-CA) under the control of the GFAP promoter (GFAP.tTA/tetO.IKK2-CA)." (PMID 34685649, 2021). "In aging-prevalent diseases, such as AD, tauopathies, Lewy body diseases, Huntington’s disease (HD), amyotrophic lateral sclerosis (ALS) and Creutzfeldt-Jakob disease, astrogliopathy is often characterized by increased GFAP and abnormal protein aggregates." (PMID 32269994, 2020). "In the transgenic (SOD1G93A/GFAP-luc) mouse model of amyotrophic lateral sclerosis, BLI revealed multiple phases of increased luminescence that closely correlate with significant increases in GFAP expression." (PMID 31572168, 2019).
Brain atrophy (32 papers, 2021 to 2026). Partial or complete wasting (loss) of brain tissue that was once present. "Higher baseline plasma GFAP and NfL were significantly associated with brain atrophy and impaired white matter microstructure." (PMID 40877465, 2026). "In the DLB group, we found that higher plasma levels of GFAP and NfL were associated with greater brain atrophy in medial temporal and frontal brain areas as well as with a higher cerebrovascular lesion load (Fazekas)." (PMID 40847319, 2025). "Higher baseline serum neurofilament light (NfL) and glial fibrillary acidic protein (GFAP) were associated with greater rate of brain atrophy over 5 years." (PMID 38805359, 2024). "Neurofilament light chain (NfL) is a novel biomarker reflecting neuroaxonal damage and associates with brain atrophy, and glial fibrillary acidic protein (GFAP) is a marker of astrocytic activation, associated with several neurodegenerative diseases." (PMID 35551210, 2022). "There was also a weak association between longitudinal GFAP and brain atrophy (β = −0.007, P = 0.040)." (PMID 36456833, 2022). "Plasma GFAP, p-tau181 and p-tau217 as well as regional brain atrophy may be useful biomarkers for neurodegenerative risk following RHI." (PMID 40481074, 2025). "Hence, our current study adds to that literature by demonstrating that the association of brain atrophy with plasma GFAP and NfL also exists in DLB patients." (PMID 40847319, 2025). "Interestingly, a previous study in aged Microcebus murinus (>7 years old, both sexes), found that increased GFAP expression was associated with brain atrophy." (PMID 40175332, 2025). "We found that increased serum NfL and GFAP levels at baseline were associated with an accelerated rate of both global and regional brain atrophy; however, only longitudinal changes in serum NfL tracked the changes in both global and regional brain volumes over 5 years." (PMID 38805359, 2024). "Taken together, our results support the notion that plasma GFAP and NfL are sensitive biomarkers for neurodegeneration, including brain atrophy and impaired integrity of white matter microstructure." (PMID 40877465, 2026). "Among these, neurofilament light chain (NfL), ubiquitin C-terminal hydrolase L1, total tau, and glial fibrillary acidic protein (GFAP) were consistently associated with CI and brain atrophy across various TBI severities and stages." (PMID 42196255, 2026). "In the subgroup of p-tau217 positive AD patients, the vaccine generated efficacy signals in preserving cognition (CDR-SB), reducing biomarkers for neurodegeneration and neuroinflammation (plasma NfL and GFAP), and slowing brain atrophy." (PMID 39800469, 2025). "In previous reports, we assessed the associations among serum NfL, GFAP, tau, and UCH‐L1 and global measures of MRI‐measured brain atrophy." (PMID 38805359, 2024). "In contrast, substantial trauma-associated elevations in t-tau, NfL, GFAP and UCH-L1 were seen, with concentrations of NfL and t-tau predictive of brain atrophy rates." (PMID 37833041, 2024). "GFAP is correlated with overall brain atrophy and decreased cortical gray matter volume, so it is reasonable to presume an association between GFAP and cognitive dysfunction." (PMID 39238198, 2024). "Given that brain atrophy scores correlate with elevated NfL and GFAP levels, 36 37 it is conceivable that higher atrophy burden in females results in higher levels of NfL and GFAP." (PMID 40486666, 2025). "Comprehensive neuropsychological assessments, FDG and tau PET scans, and plasma NfL and GFAP levels are useful and more sensitive than evaluating symptoms and visual reading of brain atrophy on MRI in the early identification of genetic svPPA patients with the MAPT mutation." (PMID 36707904, 2023).
Brain atrophy (continued). "As a confirmation, glial fibrillary acidic protein (GFAP), a marker of astrogliosis, has been measured in several genetic mutations, including C9ORF72, GRN, and MAPT, and showed to be increased only in symptomatic GRN mutation carriers, correlating also with lower cognitive scores and brain atrophy." (PMID 37628709, 2023). "Additionally, brain atrophy is commonly observed in NIID,4,41 and we found a strong correlation between GFAP levels and WMV, indicating that plasma GFAP levels correlate with disease severity of NIID." (PMID 41539185, 2026). "Similarly, plasma biomarkers GFAP, IL-17A, and lipopolysaccharide-binding protein (LBP), as well as complement factors D and C5, showed positive correlations with brain atrophy." (PMID 40305176, 2025). "The current study focuses on understanding the variability in levels of plasma pTau181, pTau217, pTau231, GFAP, and NfL in relation to the clinically used biomarkers of AD (i.e., amyloid-PET, CSF pTau181, and brain atrophy on MRI) in a cohort of patients of memory clinics." (PMID 39701863, 2025). "GFAP correlated to global brain atrophy, but not beyond ageing." (PMID 37288268, 2023). "The lack of correlation in symptomatic mutation carriers between CSF complement factors and most disease severity measures, including brain atrophy, NfL, GFAP and MMSE, indicates that complement levels probably do not increase linearly as the disease progresses." (PMID 36064709, 2022).
diabetic retinopathy (31 papers, 2009 to 2026). "In addition to the infiltrating immune cells, we investigated the activity of astrocytic and Müller cells (GFAP+ cells) that have been associated with certain progressive ocular inflammatory conditions such as diabetic retinopathy." (PMID 40156826, 2025). "Similarly, several retinal degenerative diseases associated with GFAP elevation and gliosis in Müller cells, including diabetic retinopathy and light-induced retinal degeneration, have also been linked to an increased expression of Gal-3." (PMID 25968897, 2015). "Combination therapy with Sem and rosiglitazone was studied for diabetic retinopathy in rodent animals by decreasing the GFAP expression and inhibiting oxidative stress." (PMID 40088335, 2025). "It was found that both VEGF and GFAP protein expressions were significantly upregulated in the retinal tissues of diabetic retinopathy mice when compared to control mice, while GSP treatment successfully and significantly downregulated these increases." (PMID 41409191, 2025). "Compared to control mice, mRNA expressions of both VEGF and GFAP were upregulated in the retinal tissues of diabetic retinopathy mice, which were significantly downregulated by GSP treatment." (PMID 41409191, 2025). "GFAP and vimentin, related to diabetic retinopathy and stress, were the lowest for the case of 160 μW treatment at the value of 2.607 and 0.909." (PMID 35092362, 2022). "Neuronal apoptosis, reactive gliosis, and changes in the expression of glial fibrillary acidic protein (GFAP) are all features of neurodegeneration that have been observed in animal models of diabetic retinopathy." (PMID 33809186, 2021). "LRIC alleviated diabetic retinopathy symptoms as evidenced by the increased number of retinal ganglion cells (P<0.01) and decreased glial fibrillary acidic protein (GFAP) expression level (P<0.01) in the rat retina." (PMID 30574423, 2018). "We also included in the analysis of GFAP, which is a marker of glial activation, typical phenotype of diabetic retinopathy." (PMID 28338045, 2017). "In experimental diabetic retinopathy, glial reactivity is manifested by increased GFAP immunoreactivity and content in both Müller cells and astrocytes." (PMID 27294114, 2016). "In experimental diabetic retinopathy the glial reactivity was manifested by increased GFAP immunoreactivity and content in astrocytes." (PMID 27294114, 2016). "Retinal gliosis, a salient feature of the retina under stress or injury including diabetic retinopathy, is characterized by elevated expression of the intermediate filament, glial fibrillary acidic protein (GFAP) in Müller cells and astrocytes." (PMID 24968134, 2014). "Moreover, the expressions of vascular endothelial growth factor and glial fibrillary acidic protein induced by diabetic retinopathy were remarkably reduced by GSP." (PMID 41409191, 2025). "In addition, vimentin and GFAP, related to diabetic retinopathy and retina stress, were significantly decreased in the treated group with the far red/NIR LED contact lens compared to the untreated group." (PMID 35092362, 2022). "In diabetic retinopathy, there is a decrease in GFAP immunoreactivity in astrocytes, and this is restored when insulin is administered, so insulin may regulate various aspects of retinal glial cell metabolism." (PMID 35625676, 2022). "GFAP expression increases in Müller cells in late AMD patients; moreover, changes in GFAP expression occur in response to various types of retinal insults, such as laser- or light-induced damage, diabetic retinopathy, retinal detachment, and inherited retinal degeneration." (PMID 35955937, 2022). "In addition to ERM, also hyperglycemic conditions and diabetic retinopathy are known to induce the further activation of the Müller cells and the over-expression of GFAP." (PMID 29738569, 2018). "In addition to vascular abnormalities in diabetic retinopathy, glial activation (as measured by GFAP up-regulation) has been reported." (PMID 24586745, 2014).
diabetic retinopathy (continued). "Degeneration of retinal neurons evokes an activation of glial cells (astrocytes and Müller cells), characterized by production of GFAP, which leads to release of cytokines that contribute to the maintenance of the blood retinal barrier at an early stage of diabetic retinopathy." (PMID 24167638, 2013). "However, upregulation of GFAP is unspecific, as it occurs in various retinal injury models such as axotomy, retinal ischemia, retinal detachment and diabetic retinopathy." (PMID 19806208, 2009). "Previous publications indicated the importance of VEGF and GFAP in the pathogenesis of diabetic retinopathy; therefore, we also explored GSP's effect on VEGF and GFAP in the development of diabetic retinopathy." (PMID 41409191, 2025). "GFAP is a marker for MGC activation and is upregulated in various pathological conditions, including diabetic retinopathy, retinopathy of prematurity, and glaucomatous retinal ganglion cell death." (PMID 39766850, 2024). "Compared with wild-type diabetic mice, TLR4 knockout mice exhibited improvements in diabetic retinopathy due to inhibition of the NF-kB signaling pathway and downstream inflammation, as well as downregulation of the expression of VEGF and GFAP." (PMID 36124139, 2022). "The results in the present study indicated that ATWLPPR had retinal protective effects against vascular injury, oxidative stress and up-regulation of GFAP, VEGF and ICAM-1 in a mouse model of the early stages of experimental diabetic retinopathy." (PMID 26554379, 2015). "In the present study, we demonstrate that GSP supplementation significantly alleviates diabetic retinopathy pathology, as evidenced by improved retinal thickness, reduced VEGF and GFAP expression, mitigation of oxidative stress, and activation of the Nrf2 pathway." (PMID 41409191, 2025). "This intervention reduces Müller cell apoptosis and mitigates gliosis mediated by Glial Fibrillary Acidic Protein (GFAP) overexpression, potentially helping to maintain the supportive function of Müller cells for the BRB and mitigate structural damage to the BRB in diabetic retinopathy." (PMID 40969374, 2025). "Early in the course of diabetic retinopathy, Müller cells markedly upregulate the expression of GFAP, a nonspecific response to pathophysiological conditions." (PMID 23587252, 2013). "Upregulation of glial fibrillary acidic protein (GFAP) by Müller glial cells is one of the early signs of retinal metabolic stress, which was shown in animal models and tissues from diabetic patients with no to mild nonproliferative diabetic retinopathy." (PMID 37298118, 2023).
medulloblastoma (30 papers, 2012 to 2026). A malignant, invasive embryonal neoplasm arising from the cerebellum. "Later, by using the RCAS-TVA system, we showed that specific Atoh1-negative/glial fibrillary acidic protein (GFAP)-positive brain stem cells could generate MYCN-driven medulloblastoma by using a mutationally stabilized MYCNT58A viral construct." (PMID 28333115, 2017). "Conversely, Olig2 or GFAP positivity should only be found in a small number of cells in medulloblastomas." (PMID 38201659, 2024). "GFAP, also expressed in astrocytes, has an uncertain role in medulloblastoma, although some studies suggest its expression in medulloblastoma cells." (PMID 38350915, 2024). "GFAP-cre mediated Ptch1 deletion (Ptch1lox/lox;GFAPCre) results in an aggressive medulloblastoma of the cerebellum that begins during postnatal neurogenesis and leads to a 100% mortality rate by approximately three weeks of age." (PMID 30657775, 2019). "We investigated the role of AMPKα2 in vivo in medulloblastoma using the [GFAP-tTA;TRE-SmoA1] genetically engineered mouse model of SHH-driven medulloblastoma in combination with the AMPKα2 KO mouse." (PMID 30360486, 2018). "Even Ptch1 conditional inactivation at later embryonic stage (E14.5–E16.5) leads to rapid tumor formation with 100% medulloblastoma incidence by 3–4 weeks of age in glial fibrillary acid protein (GFAP)-Cre/PtcC/C mice." (PMID 29875630, 2018). "As a matter of fact, we showed previously that GFAP-Cre-mediated 50–70% downregulation of BCCIP in mouse brain was sufficient to trigger medulloblastoma." (PMID 29047390, 2017). "Western blot analysis showed the protein levels of GFAP and synaptophysin were comparable in medulloblastoma in these three groups of mice." (PMID 27802424, 2016). "The majority of medulloblastomas exhibit neuronal differentiation in the form of immunoreactivity to synaptophysin and some also display focal glial differentiation (Glial fibrillary acidic protein (GFAP) immunopositivity)." (PMID 25101241, 2014). "Moreover, the up-regulated phosphorylation levels of Vav2 were further verified in medulloblastoma tissues from GFAP-Cre;SmoM2 +/- mice as well as in human clinical Shh type MB samples." (PMID 35154488, 2022).